E2F8 (E2F transcription factor 8)
Diseases named in the same sentence as E2F8 in open-access papers (continued):
Sharing a sentence is not in itself a finding about the gene and the disease.
E2F8 also shares sentences with these, for which no sentence is quoted: bladder cancer (2 papers); skin cancer (2); acute myeloid leukemia (1); adenocarcinoma (1); anaemia (1); anaplastic astrocytoma (1); asthma (1); brain tumors (1); cardiac hypertrophy (1); chronic myeloid leukemia (1); endocervical adenocarcinoma (1); Fanconi anaemia (1); Glucose intolerance (1); gynecological cancer (1); head and neck cancer (1); Impaired glucose tolerance (1); Infertility (1); large-cell lung carcinoma (1); lymph node metastasis (1); lymphoma (1); oligodendroglioma (1); ovarian serous carcinoma (1); prostate (1); prostate tumor (1); reproductive system disease (1); small cell lung carcinoma (1); squamous cell lung carcinoma (1).